LRRK2 (leucine rich repeat kinase 2)
Diseases named in the same sentence as LRRK2 in open-access papers (continued):
Sharing a sentence is not in itself a finding about the gene and the disease.
dementia (continued). "It is worth saying that GBA-PD patients are clinically different from LRRK2-PD or sPD as they commonly have a more aggressive course in terms of dementia and motor progression." (PMID 36720879, 2023). "Specifically, the relationship between LRRK2 and dementia was mediated by the estimated NfL level change (β = −0.717, p < 0.05)." (PMID 37699957, 2023). "LRRK2 mutation carriers show a similar pattern, with elevated AT8, GT-38 and pSyn in carriers with dementia." (PMID 31733655, 2019). "None of the PD patients had developed dementia at the time of sample collection and did not carry any LRRK2 or GBA variant." (PMID 41303651, 2025). "While there is limited literature investigating the non-motor features of PD among LRRK2 risk variant carriers, we found that p.R1628P carriers exhibited a lower frequency of dementia and orthostatic hypotension compared to non-carriers." (PMID 41253790, 2025). "Initial studies of cognitive dysfunction in patients with LRRK2-PD were based on clinical observations and suggested that dementia might occur less frequently in LRRK2-PD carrying R1441G and G2019S mutations than in sPD." (PMID 33763016, 2021). "Further, tau is not an independent disease factor in LRRK2 PD, but is associated with the degree of α-synuclein pathology and progression to dementia." (PMID 31733655, 2019). "The presence of LBs has been associated with progression to dementia in LRRK2 mutation carriers, while cases without LBs manifest primarily motor phenotypes." (PMID 31733655, 2019). "One LRRK2-PD patient was excluded because of severe dementia." (PMID 25330404, 2014). "Furthermore, we observed that the LRRK2-PD group experienced slower progression of dementia, which could be partly mediated by a slower longitudinal change in NfL levels." (PMID 37699957, 2023). "Moreover, compared to iPD, the slower progression of dementia in LRRK2-PD may be partially attributed to a slower increase in NfL levels." (PMID 37699957, 2023). "However, GBA-PD patients (N370S being the most common) show higher rates of dementia, RBD and psychosis while dual mutation carriers have the least RBD and psychosis, suggesting that LRRK2 G2019S may exert a protective effect among patients with GBA mutations." (PMID 35101134, 2022). "The presence of AD tau in iPD and LRRK2 PD could serve as diagnostic and prognostic tools to segregate cases that will or will not progress to dementia, although further work is needed to validate tau as a biomarker in PD." (PMID 31733655, 2019). "Several intensively studied dementia-affiliated genes such as APOE (apolipoprotein E), GBA1 (glucosylceramidase beta 1), LRRK2 (leucine rich repeat kinase 2), and PINK1 (PTEN induced kinase 1) encode proteins that function in the human metabolism." (PMID 36771351, 2023). "In a meta-analysis focusing on cognitive and psychiatric features, dementia was relatively rare in LRRK2-PD compared to other monogenic forms of PD with the exception of Parkin (58.8 % PINK1, 53.9 % SNCA, 50 % DJ1, 29.2 % VPS35, 15.7 % LRRK2 and 7.4 % Parkin)." (PMID 38835904, 2022). "Cognitive function is similar in LRRK2 G2019S carriers and non-carriers in some studies, while others show better cognitive function with lower rates of dementia in LRRK2 G2019S carriers." (PMID 35101134, 2022). "In our NGS study, we identified RDVs in genes which were previously associated with other neurodegenerative disorders with or without dementia, such as C19ORF12, PRKN, LRRK2, and PARK7 genes in three patients (P81, P35, P50)." (PMID 35752680, 2022). "Other studies have assessed the role of LRRK2, MAPT and SNCA for dementia in PD but results have often been inconclusive or not replicated independently." (PMID 34992521, 2021). "However, in our large PPMI cohort comprising iPD, GBA-PD, LRRK2-PD, and SNCA-PD, we did not observe a significant relationship between baseline NfL and dementia." (PMID 37699957, 2023).
Alzheimer disease (40 papers, 2009 to 2026). A progressive, neurodegenerative disease characterized by loss of function and death of nerve cells in several areas of the brain leading to loss of cognitive function such as memory and language. "Analysis of brain tissue lysates and immunohistochemistry of pathology-susceptible brain regions demonstrate that pS106-Rab12 levels are increased in Dementia with Lewy bodies (DLB), Alzheimer’s disease (AD), and PD, and in LRRK2 mutation carriers." (PMID 40661559, 2025). "About half of LRRK2-associated neurodegenerative disease displays Lewy body pathology and/or Alzheimer’s disease (AD)-associated 3R/4R tau pathology through much of the cortex." (PMID 40661559, 2025). "Tau, a protein typically associated with Alzheimer’s disease, has an emerging role in the pathogenesis of LRRK2-PD." (PMID 36233046, 2022). "We further use an antibody which selectively binds Alzheimer’s disease (AD)-type tau and use quantitative analysis of tau pathology to demonstrate that AD tau is the prominent type of tau present in LRRK2 mutation carriers." (PMID 31733655, 2019). "LRRK2 mutation has been assumed to play an upstream influence on the etiology of not just PD but also several α-synuclein and tau pathologies, including Alzheimer disease (AD)." (PMID 25391693, 2014). "However, LRRK1 has rarely been reported to be associated with a human disease except that one family was found to carry LRRK1 mutations linked to the osteosclerotic metaphyseal dysplasia (OSMD), while LRRK2 has been strongly associated with PD, Alzheimer’s disease (AD), and immune disorders." (PMID 30562929, 2018). "While disorders like schizophrenia are characterised by a wide spectrum of genetic variation including a high burden of rare variants, others may be characterised by common variants of stronger effect in genes such as LRRK2 in Parkinson’s disease (PD), or APOE in Alzheimer’s disease (AD)." (PMID 41176580, 2025). "The control group for all regions also includes a small subset of unaffected Leucine-rich repeat kinase 2 (LRRK2) positive samples and individuals with microscopic Alzheimer’s disease lesions that were insufficient for diagnosis." (PMID 39605431, 2024). "Wild-type and LRRK2G2019S knock-in (KI) mice were injected with Alzheimer’s disease (AD)-derived tau and concurrently treated with control diet or LRRK2 kinase inhibitor MLi-2 in diet targeting the IC50 or IC90 of LRRK2 based on previous research." (PMID 38438877, 2024). "Among the differentially expressed proteins, there were proteins involved either in the neurogenic process (e.g. GDF11) or in Alzheimer’s disease (e.g. LRRK2, RCAN1, NTRK2), or in both neurogenesis and Alzheimer’s disease (e.g. CREBBP, SFRP1, IL1RAP)." (PMID 36703180, 2023).
colitis (39 papers, 2012 to 2025). Inflammation of the colon. "Although our study primarily focused on DCs, research examining diverse cell populations under various inflammatory conditions is warranted to determine the mechanisms by which the LRRK2 N2081D mutation enhances colitis severity." (PMID 41031878, 2025). "Consistent with previous reports, we also observed that the LRRK2 G2019S mutation modestly increases colitis severity relative to WT animals." (PMID 41031878, 2025). "To evaluate the impact of LRRK2 mutations on colonic inflammation and colitis symptoms, we used the dextran sodium sulfate (DSS) model." (PMID 41031878, 2025). "Studies with LRRK2 KO animals suggest that LRRK2 is a regulator of colitis, susceptibility to lung cancer, and susceptibility to neurodegeneration." (PMID 39897276, 2025). "Characterizing mice carrying the LRRK2 N2081D risk variant, we found the variant exacerbates induced colitis, confirming its pathogenic role in CD." (PMID 41031878, 2025). "Since eosinophils have recently been implicated as key player in intestinal defence and colitis, it will be interesting to evaluate LRRK2 functions in these cells." (PMID 40394349, 2025). "Collectively, these results show that the Lrrk2N2081D mutation significantly exacerbates colonic inflammation and the severity of induced colitis, validating the Lrrk2N2081D model as a tool to study LRRK2-linked CD pathogenic mechanisms." (PMID 41031878, 2025). "To test this, we utilized the DSS-induced colitis model to investigate the susceptibility of LRRK2 KI mice to intestinal inflammation." (PMID 38607004, 2024). "Such enhanced proinflammatory cytokine responses to Dectin-1 ligands predispose LRRK2-TG mice to experimental colitis and thus provide a mechanistic link between polymorphisms in LRRK2 and CD." (PMID 38440723, 2024). "The objective of this study was to elucidate how gain-of-kinase activity mutant LRRK2 G2019S promotes colon tumorigenesis in a colitis-associated cancer model." (PMID 38607004, 2024). "The presence of the hyperactive G2019S LRRK2 mutation enhances the inflammatory response in experimental colitis and, remarkably, induces neuroinflammatory events in the brain confirming the gut-to-brain crosstalk." (PMID 37289222, 2023). "The Lrrk2 p.G2019S mice with colitis show reduced motor function and increased loss of dopaminergic neurons." (PMID 38098067, 2023). "Other studies in LRRK2 KO animals suggest that LRRK2 is a modulator of toxic insults, including a modulator of experimental colitis, susceptibility to carcinogen-induced lung cancer, and sensitivity to alpha-synuclein mediated nigrostriatal neurodegeneration." (PMID 33922322, 2021). "In contrast, an independent study reported exacerbated colitis in LRRK2 deficient mice, indicating that the exact relation between LRRK2 and IBD requires further investigation." (PMID 32410948, 2020). "A recent study demonstrated that the overexpression of LRRK2 leads to increased susceptibility to DSS-induced colitis in mice." (PMID 32508566, 2020). "LRRK2 deficiency leads to aberrant activation of macrophages and increased susceptibility to chemically-induced colitis in mice." (PMID 32575365, 2020). "An earlier study showed that LRRK2 deficiency led to increased susceptibility to DSS-induced colitis in mouse models by negatively regulating activation of the transcription factor NFAT." (PMID 30669622, 2019). "It is obviously of interest that the Lrrk2 (-/-) mice showed increased susceptibility to experimental colitis and enhanced levels of innate immune response." (PMID 26067490, 2015). "LRRK2 deficiency results in enhanced susceptibility to experimental colitis in mice, indicating the important role of LRRK2 in periphery inflammation and its potential association with PD." (PMID 26464797, 2015). "Paradoxically, LRRK2 deficiency exacerbates experimentally induced colitis in mice, suggesting a phenotypic role for LRRK2 in CD." (PMID 23190742, 2012).
colitis (continued). "Although further confirmation is needed, we propose that these cellular phenotypes likely contribute to the increased severity of colitis observed in LRRK2-N2081D mutation carriers by enhancing immune cell infiltration and sustaining inflammatory responses in intestinal tissue." (PMID 41031878, 2025). "Moreover, we elucidate how LRRK2 G2019S heightens the susceptibility to DSS-induced colitis in mice." (PMID 38607004, 2024). "Taken together, our findings indicate that LRRK2 KI mice are more susceptible to DSS-induced colitis than WT counterparts, and LRRK2 G2019S may promote tumorigenesis through the promotion of inflammation." (PMID 38607004, 2024). "Finally, the autophagy-related gene LRRK2, which is susceptibility locus for CD and influences inflammation in colitis models, was upregulated in both CD ileum and colon." (PMID 35190924, 2022). "However, it has previously been demonstrated that the down-regulation of Lrrk2 enhances the susceptibility of mice to DSS-induced colitis, suggesting that a loss of LRRK2 is also sufficient to increase inflammation in the gut." (PMID 32508566, 2020). "Furthermore, severe experimental colitis induced by dextran sulphate sodium (DSS) in LRRK2 deficient (Lrrk2-/-) mice was associated with enhanced nuclear localization of NFAT1." (PMID 24479879, 2014). "In regard to this, it will be important to test whether transgenic mutant LRRK2 mice are more susceptible to experimentally induced colitis, similar to the LRRK2−/− mouse, which would support a loss of function mechanism for PD mutations." (PMID 22594666, 2012). "Others have also demonstrated that Lrrk2 G2019S can render mice more vulnerable to DSS-induced colitis, or downstream consequences." (PMID 40883285, 2025). "Collectively, these studies suggest that alterations in LRRK2 are important for the prevention and treatment of colitis and related infections." (PMID 40842999, 2025). "Previous studies have demonstrated the suppressive effects of the LRRK2 kinase inhibitor LRRK2-IN-1 on cytokine production in vitro and colitis in vivo." (PMID 38607004, 2024). "In the DSS-induced acute colitis model, we observed increased necrosis in the epithelium of LRRK2 KI mice when compared with WT controls." (PMID 38607004, 2024). "Using the DSS-induced colitis model, several groups have tested the role of LRRK2 in intestinal inflammation." (PMID 38607004, 2024). "Remarkably, the administration of LRRK2-IN-1 inhibited DSS-induced colitis in both the LRRK2 KI and WT groups." (PMID 38607004, 2024). "Given the established positive correlation between colitis and colorectal cancer, our data suggest that LRRK2 G2019S-mediated colitis potentially exacerbates the pathogenesis of colorectal cancer in PD patients carrying this mutation." (PMID 38607004, 2024). "Although several studies have described LRRK2 kinase activity as playing a critical role in DSS-induced acute and chronic colitis, the underlying mechanisms remain elusive." (PMID 38607004, 2024). "Our investigation also reveals that LRRK2 G2019S promotes inflammasome activation and exacerbates gut epithelium necrosis in the colitis model." (PMID 38607004, 2024). "Later, the Baekelandt V group reported that LRRK2 G2019S KI mice exhibited more severe colitis compared to WT controls, consistent with our findings in bioRxiv." (PMID 38607004, 2024). "Subsequently, we demonstrated that the LRRK2 G2019S-GSDMD signaling axis is pivotal for the increased colitis in LRRK2 KI mice, which is now integrated into this report alongside the findings previously reported in bioRxiv." (PMID 38607004, 2024). "Through the genetic study of LRRK2 G2019S KI mice, we further elucidated that LRRK2 G2019S promotes intestinal inflammation in a DSS-induced colitis model." (PMID 38607004, 2024). "In the current DSS-induced colitis model, we found that LRRK2 G2019S promotes inflammasome activation, resulting in elevated production of IL-1β and IL-18 in the gut epithelium." (PMID 38607004, 2024).
colitis (continued). "Recent animal studies have shown that colitis in Lrrk2 p.G2019S mice is more severe than that in littermate controls or Lrrk2 wild-type mice." (PMID 38098067, 2023). "In conclusion, further research in more relevant preclinical models is needed to better understand the link between LRRK2 and colitis (Reviewed in detail in Tsafaras and Baekelandt, 2022)." (PMID 37289222, 2023). "Genetically modified mice with overexpression of LRRK2 or knocking it out show that LRRK2 is a key protein in the inflammatory response in colitis." (PMID 38196993, 2023). "In this study, we show that LRRK2 plays a crucial role in colitis, through the modulation of the immune response." (PMID 37289222, 2023). "Nevertheless, a significantly increased sensitivity was observed in the GS LRRK2 mice, which developed severe colitis symptoms." (PMID 37289222, 2023). "Pharmacological inhibition of LRRK2 significantly ameliorated the colitis phenotype based on the disease index score, especially in the last two weeks of the treatment." (PMID 37289222, 2023). "Taken together, our results link LRRK2 with the immune response in colitis and provide evidence that gut inflammation can impact brain homeostasis and contribute to neurodegeneration in PD." (PMID 37289222, 2023). "Next to the robust inflammation in the colon, the chronic DSS-experimental colitis protocol also triggered neuroinflammatory events in the GS LRRK2 mice." (PMID 37289222, 2023). "Bone marrow transplantation of wild-type cells into G2019S knock-in mice fully rescued this exacerbated response, proving the key role of mutant LRRK2 in immune cells in this experimental colitis model." (PMID 37289222, 2023). "Our data indicate that upon colitis mutant LRRK2 aggravate neurodegeneration, through a gut-to-brain-induced neuroinflammation." (PMID 37289222, 2023). "To date, a few studies have already tried to evaluate the role of LRRK2 in colitis in different rodent models with divergent results." (PMID 37289222, 2023). "LRRK2 knock-out mice have prominent colitis compared to wild-type mice upon exposure to chemical stimulants." (PMID 35897024, 2022). "By contrast, overexpression of Lrrk2 results in an increased severity of DSS-induced colitis in mice." (PMID 36142381, 2022). "Genetic association studies suggest that LRRK2/MUC19 and ATG7 deficiency aggravates intestinal inflammation in mouse models of colitis." (PMID 33904657, 2021). "Differences in experimental paradigm between these two studies make it difficult to conclude the role of LRRK2 activity in colitis." (PMID 32508566, 2020). "Future research utilizing consistent experimental colitis paradigms in LRRK2-animal models of PD are required in order to examine the effects of intestinal inflammation on PD-associated pathology in both the nigrostriatal pathway and gastrointestinal system." (PMID 32508566, 2020). "LRRK2 transgenic mice display more severe colitis induced by dextran sodium sulfate treatment than wild-type mice, which was alleviated by treatment with LRRK2 inhibitors [100●]." (PMID 32036294, 2020). "In a mouse model for UC-like pathology based on dextran sulfate sodium (DSS), transgenic mice overexpressing LRRK2 WT exhibited more severe colitis and increased proinflammatory cytokine production compared to littermate controls." (PMID 32410948, 2020). "In MPs, NFATc is retained in the cytosol by the kinase LRRK2 and Lrrk2−/− mice develop severe colitis due to overwhelming inflammation upon NFATc translocation to the nucleus." (PMID 31921172, 2019). "Liu and colleagues investigated the roles of LRRK2 in a mouse model of acute colitis induced by dextran sulphate sodium (DSS), which depends on the innate immune response." (PMID 32714591, 2018). "LRRK2 is expressed in lymphoid cells and, interestingly, Lrrk2 (-/-) mice were reported to develop more severe experimental colitis than their wild type (WT) controls." (PMID 26067490, 2015).